LDLRAP1 (low density lipoprotein receptor adaptor protein 1)
Diseases named in the same sentence as LDLRAP1 in open-access papers:
LDLRAP1 is named in the same sentence as 35 diseases in open-access papers, as found by Europe PMC text mining. Sharing a sentence is not in itself a finding about the gene and the disease. The quoted sentences say what the papers report.
familial hypercholesterolemia (44 papers, 2011 to 2026). An inheritable form of hyperlipidemia, in which there are excess lipids in the blood. "Three variants were reported for LDLRAP1, which is important in the rare forms of familial hypercholesterolemia." (PMID 37183561, 2023). "In an effort to confirm these DNA repair outcomes at different locus, we recruited a sperm donor homozygous for LDLRAP1 (g.24059 G > A, NG_008932.1) mutation located on chromosome 1 and associated with familial hypercholesterolemia (FH)." (PMID 36882397, 2023). "While involved in recessive forms of hypercholesterolemia, heterozygous variants in LDLRAP1 have been shown to increase LDL-C levels." (PMID 35323704, 2022). "Compound homozygous or heterozygous individuals for pathogenic mutations of LDLRAP1 show an autosomal recessive form of hypercholesterolemia (ARH/FHCL4) (OMIM, 603813)." (PMID 35743896, 2022). "In the recent study, Polyphen-2, when compared with SIFT, M-CAP and CADD tools, can make better pathogenicity predictions for familial hypercholesterolemia (FH) causative LDLRAP1 mutations." (PMID 36703890, 2022). "Elevated serum cholesterol levels can be found in patients with GAD and OCD, we found LDLRAP1 associated with hypercholesterolemia was differentially methylated between GAD and OCD." (PMID 36344488, 2022). "Mutations in genes associated with the autosomal recessive type of familial hypercholesterolemia—for example, in the LDLRAP1 gene—are seen in <1% of the cases." (PMID 34834584, 2021). "In this clinically ascertained patient with FH who had severe hypercholesterolemia, we found an acceptor splice-site mutation (c.345-2A>G) in intron 3 of the LDLRAP1 gene." (PMID 34425670, 2021). "A rare autosomal recessive form of familial hypercholesterolemia is produced by homozygous and compound heterozygous mutations of LDLRAP1 gene." (PMID 28577571, 2017). "However, in relation to the response to statins, patients with autosomal recessive hypercholesterolemia, a rare disorder caused by LDLRAP1 mutation, have been reported to respond better to statins than patients with homozygous hypercholesterolemia." (PMID 35215239, 2022). "In addition, the mutations in LDLRAP1 gene encoding LDL receptor adaptor protein accounts for the autosomal recessive familial hypercholesterolemia." (PMID 28577571, 2017). "In addition, mutations in LDLRAP1 gene cause familial hypercholesterolemia (FH) characterized with severe hypercholesterolemia and premature coronary artery disease." (PMID 24906453, 2014). "The low-density lipoprotein receptor adaptor protein 1 gene (LDLRAP1) at 1p36.11 (OMIM # 605747) is the only gene responsible for the recessive form of hypercholesterolemia identified to date." (PMID 35323704, 2022).
familial hypercholesterolemia (continued). "Although LDLRAP1 is involved in hypercholesterolemia, we focused on this gene because statins are involved in the regulation of blood cholesterol levels by inhibiting the mevalonate pathway, and a significant correlation has been reported between ovarian tumors and cholesterol levels." (PMID 35215239, 2022). "Familial hypercholesterolemia (FH) occurs due to an altered pathway of receptor-mediated LDL uptake due to mutations of the LDL receptor, the ApoB protein, the low-density lipoprotein receptor adapter protein 1 (LDLRAP1), or the proprotein convertase subtilisin/kexin type 9 (PCSK9) gene." (PMID 34832111, 2021). "Additionally, rare variants in LDLRAP1, LIPA, and ABCG5/8 cause a purely autosomal recessive hypercholesterolemia, in which recessive forms have hypercholesterolemia phenotypically similar to FH." (PMID 30526649, 2018). "Therefore, targeted gene sequencing analysis was performed using custom panels focusing on the exome regions of 21 lipid-associated genes, including ABCG5, ABCG8, and familial hypercholesterolemia-causing genes (LDL receptor, LDLRAP1, PCSK9, and apolipoprotein B)." (PMID 38338819, 2024). "Previous evidence indicated that LDLRAP1 dysregulation leads to low-density lipoprotein receptors on the apical surface, and reduce low-density lipoprotein uptake, thereby decreasing LDL-cholesterol metabolism, which could cause familial hypercholesterolemia." (PMID 35957912, 2022). "Thus, an oligogenic form of hypercholesterolemia is probably present in this family and high levels of LDL-C could be caused by the cumulative effect of LRP6 and CYP7A1 variants, which is aggravated by the LDLRAP1 variant." (PMID 35323704, 2022). "However, despite the addition of LDLRAP1 and PCSK9 to the list of genes that are associated with inherited hypercholesterolemia, there still appears to be a substantial number of patients with a clinical diagnosis of possible or defined FH who exhibit unknown genetic defect." (PMID 33807407, 2021).
familial hypercholesterolemia (continued). "LDLRAP1, which was extracted as a predictive marker for statin response with an inverse correlation to VDAC1, is involved in the incidence of familial hypercholesterolemia, although its association with cancer has not been reported." (PMID 35215239, 2022).
Hypercholesterolemia (27 papers, 2011 to 2026). An increased concentration of cholesterol in the blood. "A very rare autosomal recessive hypercholesterolaemia is caused by mutations in the low-density lipoprotein receptor adaptor protein 1 (LDLRAP1) gene which encodes a cytosolic protein that interacts with the cytoplasmic tail of the LDL-receptor." (PMID 28405938, 2017). "However, several studies have reported that subjects affected with heterozygous LDLRAP1 variants were associated with mild hypercholesterolaemia, but the effect of those heterozygous LDLRAP1 variants can only be definitively confirmed through extensive family screening and functional studies." (PMID 36499307, 2022).
dyslipidemia (6 papers, 2020 to 2025). "What is the underlying factor responsible for alterations in markers associated with glucose dysmetabolism (GLP-1R), dyslipidemia (LDLRAP1), ferroptosis (NFE2L2), and autophagy (SQSTM1)?" (PMID 38915346, 2024). "Mutations in different genes have been shown to cause monogenic dyslipidemia, including LDLRAP1 mutations that are involved in autosomal recessive hypercholesterolemia, ABCG5/ABCG8, involved in sitosterolemia, or LMF1, which is associated with familial chylomicronemia syndrome." (PMID 37887310, 2023). "For complex disorders, variants in genes with clear biological and clinical importance, such as LDLRAP1, SCARB1, and NPC1L1 have been identified, corresponding to approximately 25% - 30% of the genetic variance for various dyslipidemia traits." (PMID 38938445, 2024).
coronary artery disease (3 papers, 2014 to 2023).
ovarian carcinoma (3 papers, 2015 to 2025). A malignant neoplasm originating from the surface ovarian epithelium. "Validation of VDAC1 and LDLRAP1 in clinical trials is needed before off-label use of statins in ovarian cancer can be considered." (PMID 40807057, 2025). "Although the mechanisms by which VDAC1 and LDLRAP1 are involved in statin response remain to be elucidated, clinical trials in which the expression of these genes narrows down the cases of ovarian cancer will be very promising." (PMID 35215239, 2022). "To confirm this result, we evaluated VDAC1 and LDLRAP1 expression in each of the existing cell lines and human ovarian cancer ascites-derived cell lines." (PMID 35215239, 2022).
hyperlipidaemia (2 papers, 2020 to 2023).
xanthoma (2 papers, 2014 to 2020). A non-neoplastic disorder characterized by a localized collection of histiocytes containing lipid. "The double-heterozygous mother showed a severe FH phenotype (including high LDL-C, xanthomas, and CAD), suggesting that that the additional LDLRAP1 mutation leads to a more severe phenotype for xanthoma and atherosclerotic CVD in FH patients." (PMID 33519890, 2020).
atherosclerosis (1 paper, 2024). A disease characterized by the build-up of fatty material and calcium deposition in the arterial wall resulting in partial or complete occlusion of the arterial lumen.
carcinoma of the head and neck (1 paper, 2012). "The genes in the signature, LDLRAP1, PHF20, and LUC7L3, are known to be involved in carcinoma of the head and neck, tumour-associated antigens, and/or cellular signalling." (PMID 22986368, 2012).
clear cell carcinoma (1 paper, 2022). "LDLRAP1 expression was low in the serous and clear cell carcinoma cell lines and in the simvastatin-responsive cell lines 4C and 7C and high in the mucinous carcinoma cell lines and in the simvastatin-refractory cell lines 2C and 8C." (PMID 35215239, 2022).
colitis (1 paper, 2025). Inflammation of the colon. "Targets LDLRAP1 to inhibit hepatic LDL clearance; alleviates colitis." (PMID 41393953, 2025).
lung carcinoma (1 paper, 2021). "The frameshift in LDLRAP1 caused a fusion of p.W22fs in one case and was interpreted as pathogenic from InterVar, it might be deleterious in the development of lung cancer." (PMID 34540367, 2021).
lysosomal acid lipase deficiency (1 paper, 2025). "No homozygous variants were detected in the recessive genes, i.e. no autosomal recessive hypercholesterolemia (LDLRAP1), siterolemia (ABCG5/8) or lysosomal acid lipase deficiency (LIPA)." (PMID 39802654, 2025).
myocardial infarction (1 paper, 2020). Gross necrosis of the myocardium, as a result of interruption of the blood supply to the area, as in coronary thrombosis.
cancer (6 papers, 2016 to 2022). A tumor composed of atypical neoplastic, often pleomorphic cells that invade other tissues. "In lean NASH-HCC, methylation differences were seen in genes involved with cancer progression and prognosis (including HCC), such as CHCHD2, FSCN1, and ZDHHC12, and lipid metabolism, including PNPLA6 and LDLRAP1." (PMID 36474183, 2022). "However, the other two genes, LDLRAP1 and PNPLA6, have not been found to be related to cancer patients’ prognosis at present." (PMID 35957912, 2022).
autosomal dominant disease (2 papers, 2022 to 2023). Autosomal dominant form of disease.
infection (2 papers, 2019 to 2020). The state of being infected such as from the introduction of a foreign agent such as serum, vaccine, antigenic substance or organism. "In conclusion, our results suggest a role of LDLRAP1 gene in the low susceptibility to HCV-infection." (PMID 31227787, 2019).
tumor (2 papers, 2012 to 2017). "OCI-AML3 and primary tumor B cells also increased LDLRAP1 mRNA after DCA treatment or after incubation in OXPHOS medium." (PMID 28878225, 2017).
LDLRAP1 also shares sentences with these, for which no sentence is quoted: genetic disorder (3 papers); Alzheimer ́s disease (1); autosomal recessive familial adenomatous polyposis (1); breast carcinoma (1); diabetes mellitus (1); familial chylomicronemia syndrome (1); Familial hypercholesterolemia-4 (1); Hypertension (1); hypobetalipoproteinemia (1); Membranous Nephropathy (1); mucinous carcinoma (1); ovarian tumors (1); pancreatic cancer (1); septic shock (1); sickle cell anaemia (1); sitosterolemia (1); X-linked agammaglobulinemia (1).